S100A4 (S100 calcium binding protein A4)
Diseases named in the same sentence as S100A4 in open-access papers (continued):
Sharing a sentence is not in itself a finding about the gene and the disease.
pulmonary fibrosis (continued). "Our results indicated that CB2R activation exerted antifibrotic effects in vivo, and JWH133 effectively prevented BLM-induced pulmonary fibrosis in mice through the FAK/ERK/S100A4 pathway." (PMID 37957604, 2023). "The inhibition of S100A4 production with niclosamide reduces collagen deposition and attenuates lung fibrosis." (PMID 37569370, 2023). "Correspondingly, inhibitors of S100a4 are explored as a therapeutic target for the treatment of lung fibrosis." (PMID 37932771, 2023). "For example, the number of S100A4+ macrophages in BALF has been shown to correlate with the initiation of idiopathic pulmonary fibrosis." (PMID 36799806, 2023). "However, the associations among S100A4, S1P, and pulmonary fibrosis were unknown in COPD patients." (PMID 35165531, 2022). "A clinical epidemiological study demonstrated that S100A4 is elevated in the serum of patients with idiopathic pulmonary fibrosis." (PMID 35165531, 2022). "In the present study, the levels of S100A4, S1P, and related markers of pulmonary fibrosis were detected between COPD patients and control subjects." (PMID 35165531, 2022). "We identified S100A4, a calcium-binding protein that is reported to play a crucial role in idiopathic pulmonary fibrosis by stimulating fibroblast migration and activation." (PMID 35496059, 2022). "A case-control study based on the hospital population demonstrated that serum S100A4 is elevated in patients with idiopathic pulmonary fibrosis." (PMID 35165531, 2022). "Experiments in vivo and in vitro have revealed that S100A4 from fibroblasts promotes pulmonary fibrosis." (PMID 35165531, 2022). "To illustrate the molecular mechanisms of S100A4-induced activation of fibroblasts, we tested the common pathways that are involved in the incidence and progression of lung fibrosis." (PMID 35496059, 2022). "In vivo injection of human MPCs in IPF converted self-limited bleomycin-induced lung fibrosis in mice to persistent fibrosis in an S100A4-dependent manner." (PMID 34078355, 2021). "Our previous studies have shown that macrophages are a major source of soluble S100A4 in liver and lung fibrosis, 22 suggesting that macrophages contain a high abundance of S100A4." (PMID 34145030, 2021). "As said before, S100A4 was found to be secreted by a subpopulation of inflammatory macrophages and consequently promotes the development of liver fibrosis and lung fibrosis." (PMID 32307910, 2020). "Our data also showed that during the progress of bleomycin‐induced pulmonary fibrosis, a population of S100A4+CD11b+F4/80+ macrophages accumulated in lung tissue and correlated very well with the development of lung fibrosis." (PMID 32307910, 2020). "ZnO specific gene signature further englobed the overexpression of Pla2g16 (FC + 7) a membrane damage sensor; S100a4 (FC + 7) involved in macrophage-induced lung fibrosis; Rps14 (FC + 6), Rps27 (FC + 5), and Mrps15 (FC + 5), three protein synthesis regulators." (PMID 31352547, 2020). "In another study, we used the neutralizing S100A4‐specific antibody clone 3B11 (10 μg/ml) to effectively inhibit the expression of extracellular S100A4 in mice with pulmonary fibrosis and the secretion from CD11b+F4/80+ macrophages." (PMID 32307910, 2020). "The crucial role of intracellular S100A4 for fibroblasts especially in human pulmonary fibrosis renders intracellular S100A4 a good marker for this cell type in investigating the pathogenesis of pulmonary fibrosis." (PMID 32307910, 2020). "S100a4 protein levels are strongly correlated with idiopathic pulmonary fibrosis, and S100a4 has been suggested as a potential fibrotic biomarker in the liver." (PMID 31124787, 2019). "Addressing the source of soluble S100A4 in lung, we made use of in vivo mouse models of self-resolving pulmonary fibrosis that was induced by a single dose of bleomycin." (PMID 30127784, 2018).
pulmonary fibrosis (continued). "As we showed that CD11b+F4/80+ macrophages in fibrotic lung tissue express high levels of S100A4, we asked for the mode of action of exogenous S100A4 during pulmonary fibrosis." (PMID 30127784, 2018). "Accordingly, absence or neutralization of S100A4 significantly attenuated bleomycin-induced lung fibrosis in vivo." (PMID 30127784, 2018). "We show here in a model of bleomycin-induced pulmonary fibrosis that S100A4 from CD11b+F4/80+ macrophages activate fibroblasts in a process that involves the modulation of S1P levels." (PMID 30127784, 2018). "In fact, in pulmonary fibrosis, a subpopulation of S100A4+ cells co-expresses CD45, a hematopoietic cell marker." (PMID 30127784, 2018). "Due partly to its various cellular origins, the exact role of S100A4 in the development of lung fibrosis remains elusive." (PMID 30127784, 2018). "Still, our results suggest that S100a4 warrants further investigation as a therapeutic target in pulmonary fibrosis." (PMID 29910813, 2018). "The function of S100A4 from macrophages we show here is an important addition to understand cellular mechanisms of pulmonary fibrosis." (PMID 30127784, 2018). "Increased numbers of S100A4+ macrophages were also found in lung tissues of bleomycin-treated mice during the development of pulmonary fibrosis." (PMID 30127784, 2018). "Here, we show that in the bronchoalveolar lavage fluid, numbers of S100A4+ macrophages correlated well with S100A4 protein levels and occurrence of idiopathic pulmonary fibrosis (IPF) in patients." (PMID 30127784, 2018). "S100a4 was found to be strongly upregulated in BALF of two independent murine models of pulmonary fibrosis." (PMID 29910813, 2018). "A mouse model of bleomycin-induced pulmonary fibrosis demonstrated S100A4+ macrophages as main source for extracellular S100A4 in the inflammatory phase." (PMID 30127784, 2018). "The role of S100A4 in these cells during induction and progress of pulmonary fibrosis and IPF is elusive." (PMID 30127784, 2018). "We provided the following lines of evidence to demonstrate a profibrotic role of extracellular S100a4 in pulmonary fibrosis: (i) recombinant S100a4 protein had cell growth-promoting properties on lung fibroblasts." (PMID 29910813, 2018). "A subpopulation of macrophages was the major source for S100A4 in our model of bleomycin-induced pulmonary fibrosis and in human IPF." (PMID 30127784, 2018). "Research indicates that S100A4 confers idiopathic pulmonary fibrosis lungs harboring fibrogenic mesenchymal progenitor cells with fibrogenicity." (PMID 29204268, 2017). "Similarly in lung fibrosis, S100A4 is highly expressed by tissue resident alveolar macrophages and bone-marrow-derived, M2-like macrophages." (PMID 40078995, 2025). "S100A4 has been shown to be significantly upregulated in idiopathic pulmonary fibrosis." (PMID 40787447, 2025). "The inhibition of S100A4 reduces histological evidence of lung fibrosis." (PMID 37569370, 2023). "Moreover, S100A4 has been identified as a contributory factor in idiopathic pulmonary fibrosis wherein the protein is highly expressed in mesenchymal progenitor cells and crucial to their fibrogenic transition to idiopathic pulmonary fibroblasts." (PMID 37090702, 2023). "Therapeutic strategies by targeting S100A4 go beyond the field of lung fibrosis." (PMID 36817136, 2023). "Recently, it was shown that S100A4 from fibroblasts promotes pulmonary fibrosis." (PMID 35165531, 2022). "Recently, it has been found that S100A4 can promote pulmonary fibrosis via fibroblast activation." (PMID 35165531, 2022). "Furthermore, increasing evidences indicate that S100A4 participate in the process of pulmonary fibrosis." (PMID 35379204, 2022). "Meanwhile, the levels of S100A4 and pulmonary fibrosis were detected in patients with COPD." (PMID 35165531, 2022). "From these findings, we speculate that main origin of serum S100A4 is lung fibrosis such as IP areas and there is little bias due to lung cancers." (PMID 34078355, 2021).
pulmonary fibrosis (continued). "Reportedly, S100A4 promotes lung fibrosis via proliferation and activation of fibroblasts." (PMID 34078355, 2021). "In the other study on extracellular S100A4 and pulmonary fibrosis, researchers used niclosamide (20 mg/kg) to inhibit the expression of extracellular S100A4 in mice with pulmonary fibrosis, while using S100A4‐specific siRNA to inhibit the secretion of S100A4 from M2 macrophages." (PMID 32307910, 2020). "Interestingly, our recently published data found increased S100A4 protein level in human bronchoalveolar lavage fluid of idiopathic pulmonary fibrosis (IPF) patients." (PMID 32307910, 2020). "First, we asked whether S100A4 expression levels in the lungs related to the extent of human pulmonary fibrosis." (PMID 30127784, 2018). "We next tested the potential of neutralizing S100A4 in preventing lung fibrosis in vivo." (PMID 30127784, 2018). "Finally, we inhibit S100a4 in vivo in the bleomycin-induced lung fibrosis model by treatment with niclosamide." (PMID 29910813, 2018). "S100A4, a calcium-binding protein, can promote pulmonary fibrosis via fibroblast activation." (PMID 30127784, 2018). "Here, we hypothesized that also in pulmonary fibrosis, M2 macrophages produce and secrete S100a4, and that the secreted S100a4 induces proliferation and activation of fibroblasts." (PMID 29910813, 2018). "Therefore, macrophage-derived S100A4 is necessary and sufficient for the induction of lung fibrosis in mice." (PMID 30127784, 2018). "Since lung fibrosis is also driven by monocyte-derived macrophages, we hypothesized that macrophage-derived S100a4 might also contribute to the development of lung fibrosis." (PMID 29910813, 2018). "Given the ability of calcimycin and niclosamide to inhibit S100a4 expression in primary AMs in vitro, we asked whether inhibition of S100a4 in vivo could attenuate the development of pulmonary fibrosis." (PMID 29910813, 2018). "Because of the increase in S100A4 expression in remodeled intrapulmonary arteries, neutralizing antibodies of S100A4 may prevent vascular remodeling of lung fibrosis." (PMID 29204268, 2017). "Importantly, the S100A4 KO mice were significantly protected from bleomycin-induced lung fibrosis." (PMID 38072048, 2024). "Thus, the role of macrophage-derived S100A4 in human lung fibrosis requires further investigations." (PMID 29910813, 2018). "Finally, we inhibit S100a4 in vivo with niclosamide in the bleomycin-induced lung fibrosis model." (PMID 29910813, 2018). "Thus, we hypothesized that also in pulmonary fibrosis, M2 macrophages produce and secrete S100a4, and that secreted S100a4 induces the proliferation and activation of fibroblasts." (PMID 29910813, 2018). "Inhibition of S100a4 might represent a potential therapeutic strategy for pulmonary fibrosis." (PMID 29910813, 2018). "Thus, S100a4 might serve as a cytokine-like factor indirectly promoting the pathogenesis of lung fibrosis." (PMID 29910813, 2018). "Thus, it is conceivable that also in lung fibrosis, macrophages could be an important cellular source of S100a4." (PMID 29910813, 2018). "WikiPathways enrichment analysis indicated substantial enrichment of multiple fibrosis-related pathways, including the lung fibrosis and TGF-β signaling pathways, among the differentially expressed genes in S100a4-expressing macrophages." (PMID 41031892, 2025). "In lung samples from human idiopathic pulmonary fibrosis (IPF) patients, S100A4-positive macrophages co-express CD163, another M2-like macrophage marker, suggesting S100A4 expression is in M2-like macrophages." (PMID 40078995, 2025). "In this study, MET blocked α-smooth muscle actin (α-SMA) accumulation in vivo accompanied with S100A4 expression and STAT3 phosphorylation inhibition, resulting in attenuating the progression of lung fibrosis after BLM administration." (PMID 36817136, 2023). "And upregulation of S100A4 was observed in the serum and bronchoalveolar lavage fluid (BALF) of idiopathic pulmonary fibrosis (IPF) patients." (PMID 35379204, 2022).
pulmonary fibrosis (continued). "Most importantly, niclosamide treatment of bleomycin-instilled mice significantly reduced both the amount of S100a4 in the BAL fluid and the development of lung fibrosis in 50% of the treated mice." (PMID 29910813, 2018). "Since the S100A4 protein in the BALF of IPF patients was increased, our results provide a basis for improving the diagnosis and supply new potential targets of pulmonary fibrosis therapy." (PMID 30127784, 2018). "In this study, significant increase in lung fibrosis was observed 1 week after bleomycin administration, which parallels the increase of MMP-2, S100A4, and α-SMA protein levels." (PMID 26819949, 2015). "A previous study in an animal model demonstrated that approximately one-third of the S100A4-positive fibroblasts were derived from lung epithelium 2 weeks after bleomycin administration, suggesting that EMT contributes to bleomycin-induced lung fibrosis." (PMID 26819949, 2015). "Identifying potential biomarkers of targeted inhibition by MLN0128 will be important for designing clinical trials in pulmonary fibrosis patients- PAI-1, FN, and S100A4 are potential biomarkers since they are inhibited by MLN0128 in the bleomycin model." (PMID 25162417, 2014). "Collectively, these findings define a mechanistic link between S100A4-mediated fibroblast survival and activation that drives pathological matrix remodeling and identify S100A4 and ERK as potential therapeutic targets in pulmonary fibrosis." (PMID 42287596, 2026). "Consequently, we observed an up-regulation of p-FAK, p-ERK, and S100A4.Moreover, the overexpression of FAK hindered the inhibitory effects of JWH133 on BLM-induced pulmonary fibrosis in mice." (PMID 37957604, 2023). "In addition, activated Smad signals stimulated subsignals, such as to levels of type I collagen (Col1), α-smooth muscle actin (Acta2/α-SMA), and fibroblast-specific protein 1 (Fsp1/S100A4), related to collagen accumulation and lung fibrosis." (PMID 37107342, 2023). "Moreover, the numbers of S100A4-positive macrophages were correlated with S100A4 levels in BALF of IPF patients and S100A4-positive macrophages were main source for extracellular S100A4 in the inflammatory phase of bleomycin-induced pulmonary fibrosis." (PMID 35379204, 2022). "S100A4 promoted the proliferation of lung fibroblasts and also drive myofibroblast differentiation by inducing the expression of the α-SMA and collagen I, suggesting a critical role of S100A4 in deposition of collagen and profusion of fibroblastic foci in pulmonary fibrosis." (PMID 35379204, 2022).
lung carcinoma (34 papers, 2010 to 2025). "S100A4 and S100B overexpression is associated with poor prognosis and tumor metastasis in lung cancer (seeTable 2for roles in lung diseases)." (PMID 41164170, 2025). "RAGE is a multi-ligand receptor known to contribute to inflammation and cancer progression through its interaction with S100A4, a calcium-binding protein associated with metastasis and poor prognosis in lung cancer." (PMID 41155277, 2025). "For example, the S100A4/NF-κB/MMP9 signaling axis has been shown to promote lung cancer invasion and associate with poor overall survival of NSCLC patients." (PMID 29069865, 2017). "S100A4 is associated with increased cell growth and metastatic capacity of lung cancer cells, and, PCNA plays an important role in DNA replication and repair." (PMID 26351076, 2015). "In lung cancer, experimental models have shown that there is an association between S100A4 expression and motile and invasive abilities, and that suppression of S100A4 results in reduced metastatic potential." (PMID 22853000, 2012). "S100A4 influences lung cancer cell metabolism by regulating mitochondrial function and oxygen consumption, with reduced levels promoting a shift to glycolysis and less aggressive behavior." (PMID 41164170, 2025). "SFPQ or S100A4 was knocked down with shRNA in lung cancer cells (with scrambled shRNA used as a control), and SFPQ and S100A4 expression levels and SFPQ/S100A4 complex were inhibited." (PMID 40770831, 2025). "Overall, these findings provide strong evidence that p38-MAPK activation mediates the suppression of hsa-miR-125b-5p while promoting MMP-2 expression in response to S100A4-RAGE signaling in human lung cancer cells." (PMID 41155277, 2025). "The cell invasion and migration marker MMP2 was reduced in those lung cancer cells with SFPQ or S100A4 knockdown." (PMID 40770831, 2025). "Although S100A4 and α-smooth muscle actin are conventionally recognized as markers for lung cancer CAFs, their expression levels exhibit considerable variation among CAFs sourced from different biopsies." (PMID 39403603, 2024). "Quantitative analysis of oxygen consumption rate (OCR) data reveals that S100A4 knockdown significantly decreases basal respiration, maximal respiration, and spare capacity in lung cancer cells, indicating a predominant effect on mitochondrial respiration." (PMID 39179991, 2024). "By doing this, this paper provides a review of the evidence for S100A4 in lung cancer, chronic obstructive pulmonary disease (COPD), asthma, IPF and pulmonary hypertension." (PMID 37026957, 2023). "S100A4 was demonstrated to be involved in several lung diseases, including lung cancer, COPD, asthma, pulmonary hypertension, and IPF." (PMID 37026957, 2023). "Although a study with a larger sample size is necessary to confirm our findings, the serum level of S100A4 appears to be a significant predictor of AE of IP after lung resection for lung cancer." (PMID 34078355, 2021). "Several studies have shown that expression of S100A4 in IHC study is a prognostic factor for lung cancer, and lung cancer subtype or stage can affect the serum level of S100A4." (PMID 34078355, 2021). "S100A4 seems to be an important player in the development and metastasis of lung cancer, promoting tumour cell proliferation and motility." (PMID 32722137, 2020). "In this study we showed for the first time that S100A4 plays key roles in lung cancer development by inhibiting autophagy." (PMID 29449540, 2018). "Silencing of S100A4 consistently led to an increased Beclin1, Bax and LC3 conversion and reduced p62 level, which was reversed by S100A4 treatment to lung cancer cells once again." (PMID 29449540, 2018). "We confirmed that β-catenin was overexpressed and found that both the cytoplasmic and nuclear expression of S100A4 were also upregulated following overexpression of β-catenin in lung cancer cells by western blot." (PMID 29449540, 2018).